MIR3670-4 (microRNA 3670-4)
Synonyms: hsa-mir-3670-4
Gene: MicroRNA gene on chromosome 16 (18,488,301 to 18,488,365, reverse strand). Ensembl gene ENSG00000274025.
Homologues: Paralogues in human: MIR3670-1 (100% identical), MIR3670-2 (100% identical), MIR3670-3 (100% identical).